AR (androgen receptor)
Diseases named in the same sentence as AR in open-access papers (continued):
Sharing a sentence is not in itself a finding about the gene and the disease.
nephrolithiasis (10 papers, 2014 to 2024). The presence of a calculus in the pelvis of the kidney; this is most often composed of mineral salts and proteins. "It is well-known that the ECM-receptor interaction pathway was associated with tissue fibrosis and the androgen receptor mechanisms in nephrolithiasis, and renal ischemia/reperfusion injury." (PMID 30200873, 2018). "Our data suggest the important role of AR, miRNA and CSF-1 signaling in human nephrolithiasis pathogenesis." (PMID 37093310, 2023). "Variation in the number of AR gene CAG repeat and ER gene TA repeat polymorphisms were associated with increased susceptibility to recurrent kidney stones among males as shown in individual studies." (PMID 33956883, 2021). "Androgen receptor signaling plays an important role in the pathophysiology of renal calculi formation." (PMID 32182733, 2020). "A clinical study showed that strong AR-positive signals and a relatively higher level of AR transcription correlated with kidney stones and that men manifested a more frequent presence of stones than women." (PMID 31100850, 2019). "In contrast, strong AR-positive signals and a relatively higher level of AR transcript correlate with kidney stones." (PMID 31100850, 2019). "Taken together, these results suggest that a sex difference with higher androgen/AR signaling exists in male patients with kidney stones." (PMID 24956378, 2014). "The incidence of nephrolithiasis in males appears to be three times higher than that in females, indicating that androgens and AR might play an important role in the formation of kidney stones." (PMID 39588149, 2024). "Moreover, they were found to be upregulated in tubular epithelial cells of patients with hyperoxaluria which suggests the important role of androgen/AR axis enhancement in kidney stones formation." (PMID 37093310, 2023). "The results demonstrated that female and castrated male mice were not susceptible to CaOx-induced nephrolithiasis, suggesting AR signal was involved in nephrolithiasis." (PMID 30819186, 2019). "To test the hypothesis that the AR accounts, at least in part, for the sex difference in kidney stone formation we used the cre-loxP system to knock out the AR." (PMID 24956378, 2014). "Males develop kidney stones far more frequently than females with a ratio of 2–3:1, suggesting that androgen receptor (AR) signaling might play a key role in the development of nephrolithiasis." (PMID 24956378, 2014). "The underlying mechanisms by which androgen and its receptor, the androgen receptor (AR), play roles in kidney stone formation remains unclear." (PMID 24956378, 2014). "However, androgen and AR signaling may promote kidney stone formation and aggravate renal injury since the plasma testosterone level and AR expression in the kidneys are up-regulated in men with nephrolithiasis." (PMID 34248618, 2021). "Using cell-specific AR knockout (ARKO) mouse models and the newly developed AR degradation enhancer, ASC-J9 (12, –, 15), we demonstrated that the AR in hepatocytes and kidney epithelial cells promotes oxalate/CaOx formation in the early stages of kidney stone formation." (PMID 24956378, 2014).
Atrophy (9 papers, 2014 to 2025). Any weakening or degeneration, especially through lack of use. "The dose regimen appears to significantly affect the impact of chlormadinone acetate, leading to varying degrees of prostate atrophy correlated with the degree of interaction with the androgen receptor, as demonstrated by immunohistochemistry." (PMID 39852945, 2025). "AR signalling has been shown to regulate spine density in hippocampal pyramidal neurons and attenuates dendritic atrophy in spinal MNs, in addition, providing neuroprotection to a range of neurons." (PMID 35273564, 2022). "In addition, we observed strong connectivity of ATXN2 and AR with HTT in the pons that has been described to undergo atrophy in SCA2." (PMID 29249939, 2017). "In SBMA, polyglutamine expansion in the AR may result in aberrant and sustained activation of mTOR that in turn can contribute to muscle atrophy during disease progression." (PMID 26971100, 2016). "Another compound, pyrvinium pamoate, an FDA approved anthelmintic drug, binds non-competitively to a domain of AR that is distinct from ligand binding domain, induces prostate atrophy in vivo and maybe active in the setting of ligand independent AR signaling." (PMID 25277175, 2014). "A total of 20 genes were found to overlapacross the four groups.Note that some of these genes were also differentially expressed in other models likeHuntington’s disease (HD;), AR knock out (ARKO;), and Atrophy." (PMID 25719894, 2015). "The SBMA model chosen for the study expresses the human AR transgene with 100 glutamine residues (AR100Q) and recapitulates the main features of the SBMA phenotype, with androgen-dependent muscle atrophy, reduced grip strength, denervation, and shortened survival, starting at 7 weeks of age." (PMID 34417184, 2021).
Micropenis (9 papers, 2013 to 2025). "Although all three present with micropenis, patient DSD-0115 with ATRX P1548L had right cryptorchidism, laterla hernia, and hyposmia, while DSD-0260 with both ATRX and AR variants didn’t show any other phenotypes in recorded." (PMID 39285472, 2024). "Transcriptional activity of AR is essential for normal penile growth, as inhibition of androgen in the neonatal phase induces micropenis in mice." (PMID 32358507, 2020). "Several studies have addressed factors influencing the efficacy of TRT in pediatric patients with micropenis such as mutations in steroid 5α‐reductase type 2 gene (SRD5A2) and androgen receptor (AR), which have been identified as potential causes of poor response to TRT." (PMID 40813749, 2025).
myocarditis (9 papers, 2011 to 2025). Myocarditis is a condition that is characterized by inflammation of the heart muscle (myocardium). "In this study, we present evidence that the risk of toxic myocarditis after treatment with androgen receptor inhibitors may be related to MR and GR polymorphisms through increased MR activity elicited by enzalutamide." (PMID 35740293, 2022). "The event-free survival using the combined endpoint of MCS, HTx, or death was significantly lower in MYC patients with anti-β-AR Ab levels below the median as compared to myocarditis patients with anti-β-AR Ab levels ≥ median (anti-β1/2/3-AR Ab: p = 0.049)." (PMID 35573966, 2022). "Next we determined ER and AR expression in the heart using qRT-PCR of female mice with myocarditis housed in glass vs. plastic cages with food and bedding that did not contain soy." (PMID 31551929, 2019). "Studies have found that BPA can bind to the AR, which could then directly activate the AR, leading to increased myocarditis in males." (PMID 34445539, 2021). "Therefore, suppressed AR expression in macrophages may be a therapeutic method in myocarditis, especially in males." (PMID 30956636, 2019). "We found that plastic cages significantly increased AR (p = 0.007) expression in females during acute myocarditis compared to glass cages, but did not significantly alter ER expression in the heart." (PMID 31551929, 2019).
neuroendocrine prostate tumors (9 papers, 2017 to 2026). "In more extreme cases, tumor cells switch off AR expression entirely and transition into more aggressive, AR-independent neuroendocrine prostate tumors." (PMID 41343245, 2026). "Neuroendocrine prostatic carcinoma (NEPC) with adequate morphology and loss of AR expression was seen in the RP specimen from one patient (Patient 1) and in metastases from two patients (Patients 1 and 7)." (PMID 35220606, 2022). "This profound phenotypic switch, as a consequence of selective pressure from ADT or potent antiandrogens, from tumors with adenocarcinoma histologic features that express AR to AR-negative neuroendocrine prostate tumors, has been termed lineage plasticity." (PMID 28604629, 2017). "This profound phenotypic shift, as a result of selection pressure from ADT or potent antiandrogens, from tumors with histological features of adenocarcinoma that express AR to AR-negative neuroendocrine prostate tumors has been termed lineage plasticity." (PMID 36176747, 2022). "The CDX also expresses a neuroendocrine phenotype positive for synaptophysin, chromogranin, NSE, and absence of PSA and AR, and reflects the functional state of neuroendocrine prostate carcinoma in being unresponsive to androgen deprivation." (PMID 32313004, 2020). "On the other hand, PCa cells with no AR expression may also be accumulated, and thus, the tumor progression is no longer dependent on AR signaling, such as the neuroendocrine prostate tumor." (PMID 34681745, 2021).
sarcoma (9 papers, 2016 to 2026). A usually aggressive malignant neoplasm of the soft tissue or bone. "Moreover, several sarcoma-associated gene mutations were found, including AR mutation (p.G473del, 11.11%), AXL mutation (p.T45P, 8.11%), and ETV5 mutation (p.F11Y, 33.33%)." (PMID 36153506, 2022). "Here, we demonstrate that AR is highly expressed in DSRCT relative to other fusion-driven sarcomas and that the AR antagonists enzalutamide and flutamide reduce DSRCT growth." (PMID 38575753, 2024). "Though enriched in oncoproteins, our RPPA array ranked AR as the most differentially expressed protein compared to ES, its closest molecular sarcoma subtype." (PMID 35650195, 2022). "DSRCT tumors express significantly higher levels of AR than the four other sarcoma types." (PMID 38575753, 2024). "AR genes were commonly differential expressed in most tumors compared with their corresponding normal tissues, except for Pheochromocytoma and Paraganglioma (PCPG) and Sarcoma (SARC)." (PMID 36479101, 2022). "We then intersected these AR-targeted enhancer peaks with highly expressed genes in DSRCT (FC > 1.5, adjusted p value < 0.05 in comparison to other sarcoma subtypes)." (PMID 35650195, 2022). "Notably, iP300w displayed superior efficacy against CIC::DUX4 sarcoma compared to A-485, another P300/CBP inhibitor from the same spirocyclic chemical series found to be effective against certain hematological malignancies, androgen receptor-positive prostate cancer, and NUT midline carcinoma." (PMID 39367409, 2024). "Particularly, sarcoma (SARC) and skin cutaneous melanoma (SKCM) exhibited the highest degree of negative correlations between AR activity and immune infiltration." (PMID 41486951, 2026).
seminoma (9 papers, 2012 to 2025). A radiosensitive malignant germ cell tumor found in the testis (especially undescended), and extragonadal sites (anterior mediastinum and pineal gland). "Furthermore, an association between GGN repeats in AR and the risk of TC was found in studies with a sample size > 200 and in the mid-latitude and seminoma subgroups." (PMID 26885616, 2016). "There is a significantly increased testicular germ cell tumor risk among men with shortened AR CAG repeat length which leads to increased AR transactivation that may be involved in seminoma development or progression of CIS/ITGCN to seminoma." (PMID 24922532, 2014). "In this study, we show that the androgen/AR signal suppressed the cell growth of seminomas (SEs), a type of TGCT, in vitro and in vivo." (PMID 27144435, 2016). "In a small study of seminomas, AR expression was detected in 45% of cases (N = 18) [S44]." (PMID 25595907, 2015). "AR methylation on CpG sites was not statistically significant between seminoma and nonseminoma tissues." (PMID 40358182, 2025). "There was no AR staining in embryonal carcinoma, mature teratoma, seminoma, or mixed germ cell tumors, although trace AR expression was found in 3 out of 5 cases of endodermal sinus tumors [S43]." (PMID 25595907, 2015). "This suggests that an increased AR transactivation may be involved in the development of seminoma and/or progression of carcinoma in situ (CIS) to seminoma." (PMID 23230429, 2012). "Study of various types of testicular histologies (SCO, MA, HS, seminoma, nonseminomatous germ cell tumor) for USP26 and AR expression is required." (PMID 24922532, 2014).
Sepsis (9 papers, 2009 to 2025). Sepsis is defined as life-threatening organ dysfunction caused by a dysregulated host response to infection. "It is worthwhile to investigate whether Deh can attenuate the progression of sepsis‐associated AKI by early regulation of AR and CHEM5." (PMID 38629726, 2024). "Multiple findings support a causal role for the AR pathway in sepsis." (PMID 34888328, 2021). "Secondary bacterial infections frequently complicate severe COVID-19 pneumonia and we hypothesize that increased AR pathway activity may be indicative of immunosuppression and high risk at sepsis, explaining the benefit of anti-androgen therapy in this setting." (PMID 34888328, 2021). "Thus, AR PAS in the normal range was associated with sepsis survival, at least in children." (PMID 34888328, 2021). "In addition to diagnosing sepsis, and prediction of prognosis, we hypothesize that the AR pathway activity assay may find clinical utility in prediction of risk at serious infectious complications in the period after surviving sepsis." (PMID 34888328, 2021). "In whole blood of sepsis patients, we previously reported abnormally active AR and TGFβ and a trend towards increased activity of NFκB and JAK-STAT3 STPs." (PMID 39996782, 2025). "Compared to control samples of sepsis patients (PBMCs) and healthy subjects, control samples in the in vitro studies had higher mean NFκB, AR, and JAK-STAT3 PAS (both in PBMCs and whole blood) and higher TGFβ PAS (in whole blood)." (PMID 39996782, 2025). "Our data suggest that the loss of hepatic HNF4α impairs the expression of several other nuclear receptors besides PPARα, including RXRα, FXR, CAR, AR and LXRα, and therefore has a broad downstream impact in sepsis." (PMID 39261648, 2024). "AR pathway activity tended to be lower for sepsis survivors at day three after diagnosis, decreased between Day 1 and Day 3 of sepsis in survivor patients and." (PMID 34888328, 2021). "For the AR, ER, TGFβ, and NFκB pathways putative roles in sepsis have been described, generally in relation to specific immune cell types." (PMID 34888328, 2021). "For diagnosis of pediatric sepsis, the AR pathway assay showed high sensitivity (77%) and specificity (97%), with a positive prediction value (PPV) of 99% and negative prediction value (NPV) of 50%." (PMID 34888328, 2021). "The role of testosterone in the suppression of the immune system in the sepsis model has been confirmed by using the antagonist of the AR, flutamide that in turn improves survival and organ function in male mice." (PMID 29925409, 2018). "Moreover, it has been shown that androgen receptor antagonism improves compromised immune functions and reduces mortality for sepsis in both preclinical and clinical studies." (PMID 39199203, 2024). "Although not significant, results from these independent clinical studies (children and adults) suggest that AR pathway activity within the normal range may be favorable in patients with sepsis." (PMID 34888328, 2021). "Some studies suggest that the AR pathway may be a useful drug target in sepsis: testosterone blockade in patients with hemorrhage improved the prognosis if subsequently sepsis developed." (PMID 34888328, 2021). "In summary, our current results show initial results supporting clinical validity and potential clinical utility of measuring activity of the AR and TGFβ signal transduction pathways in patients with sepsis, fulfilling the basic requirements for biomarker assays." (PMID 34888328, 2021). "Indeed, both GR and AR signaling are known to be immunosuppressive in sepsis." (PMID 39996782, 2025). "Also AR pathway blockade reduced mortality in a preclinical mouse model for sepsis." (PMID 34888328, 2021). "Within the perspective of the current study, we hypothesize that the latter group with normal AR pathway activity did not have sepsis at admission and was at lower risk to develop sepsis, possibly not needing hospital admission." (PMID 34888328, 2021).
Sepsis (continued). "In summary, we found that PBMCs from sepsis patients and from the in vitro sepsis model shared a similar STP activity profile, except for increased AR STP activity in Gram-positive sepsis patients." (PMID 39996782, 2025). "We previously reported increased AR and TGFβ STP activity (and a trend towards higher NFκB and JAK-STAT3 STP activity) in whole blood of adult and pediatric sepsis patients." (PMID 39996782, 2025). "In whole blood sepsis models, increased activity of NFκB, JAK-STAT1/2, and JAK-STAT3 STPs was found, while in vivo administration of LPS also increased AR and TGFβ STP activity." (PMID 39996782, 2025). "Targeted drugs are available against the AR, TGFβ, MAPK-AP1, NFκB, and JAK-STAT3 pathways, all involved in immune responses, offering a new perspective on treating sepsis." (PMID 34888328, 2021). "Using the pediatric upper threshold of the normal range of AR and TGFβ PAS, sensitivity, specificity, PPV, and NPV for diagnosis and prediction of survival in a pediatric sepsis patient were calculated, and a ROC curve was generated." (PMID 34888328, 2021). "Measurement of activity of the androgen receptor (AR) pathway, and to a lesser extent the TGFβ pathway, in a whole blood sample is shown to have value for sepsis diagnosis and prediction of prognosis in a sepsis patient, and may lead to novel personalized treatment options." (PMID 34888328, 2021). "No consistent differences in AR and TGFβ pathway activity scores were observed between men and women, between patients categorized as “sepsis” vs. “septic shock”, nor between patients categorized as “SAPSII-low” and “SAPSII-high”." (PMID 34888328, 2021). "In pediatric sepsis patients who survived, AR (but not TGFβ) pathway activity showed a trend toward lower PAS, within the PAS range of healthy controls." (PMID 34888328, 2021). "PAS scores for the AR, ER, MAPK-AP1, FOXO-PI3K, JAK-STAT1/2, JAK-STAT3, Notch, Hedgehog, TGFβ, and NFκB pathways were measured using target gene expression data of whole blood samples from clinical studies on children and adults with sepsis and septic shock." (PMID 34888328, 2021). "While suggestive of a role for the AR pathway in the pathophysiology of sepsis, we are not aware of any clinical studies investigating AR pathway targeted drugs in human sepsis patients." (PMID 34888328, 2021). "Activity of the AR pathway, and with exception of clinical study GSE57065, also of the TGFβ pathway, were consistently and significantly increased in pediatric and adult patients with sepsis and septic shock." (PMID 34888328, 2021). "To investigate whether increased α2-AR expression in sepsis leads to enhanced receptor binding, we incubated KCs isolated from sham-operated or CLP animals with [3H]-yohimbine, a radio-labeled α2-specific AR antagonist." (PMID 19430535, 2009). "Another study revealed that suppression of androgen receptor (AR) attenuates sepsis-induced acute lung injury (ALI) by inhibiting M1 macrophage polarization and pro-inflammatory cytokine secretion, further validating the regulatory relationship between AR and M1 macrophages." (PMID 40894073, 2025). "AR and TGFβ STP activity appeared to be increased in the in vivo whole blood model (human endotoxemia) and in patients with sepsis, but not in the in vitro whole blood model." (PMID 39996782, 2025).